NOTCH3 (notch receptor 3)
Description:
Functions as a receptor for membrane-bound ligands Jagged1, Jagged2 and Delta1 to regulate cell-fate determination. Upon ligand activation through the released notch intracellular domain (NICD), it forms a transcriptional activator complex with RBPJ/RBPSUH and activates genes of the enhancer of split locus. Affects the implementation of differentiation, proliferation and apoptotic programs (By similarity).
Synonyms: CASIL; CADASIL; CADASIL1; CARASIL1; FPLD1; IMF2; LMNS
Tractability: Small molecule: a high-quality ligand is known. Antibody: a drug acting on it is in phase 2 or 3 trials; UniProt places it where antibodies can reach, with high confidence; its Gene Ontology location is reachable by antibodies, with high confidence; UniProt predicts a signal peptide or a membrane-spanning region; the Human Protein Atlas places it where antibodies can reach. PROTAC: ubiquitination databases record sites on it; a small molecule that binds it is known.
Target class: Membrane receptor
Gene: Protein-coding gene on chromosome 19 (15,159,038 to 15,200,996, reverse strand). Ensembl gene ENSG00000074181.
Subcellular location: Cell membrane; Nucleus (Notch 3 intracellular domain)
Subcellular location (Human Protein Atlas): Nucleoplasm; Plasma membrane
Pathways (Reactome):
Signal Transduction: NOTCH3 Activation and Transmission of Signal to the Nucleus; NOTCH3 Intracellular Domain Regulates Transcription; Noncanonical activation of NOTCH3; Pre-NOTCH Processing in Golgi; Pre-NOTCH Processing in the Endoplasmic Reticulum; Pre-NOTCH Transcription and Translation
Disease: Defective LFNG causes SCDO3
Gene expression (Transcription): Notch-HLH transcription pathway
Gene Ontology:
Molecular function: cadherin binding; identical protein binding; protein binding; signaling receptor activity; calcium ion binding; enzyme binding
Biological process: Notch signaling pathway; positive regulation of miRNA transcription; axon guidance; cell differentiation; glomerular capillary formation; positive regulation of smooth muscle cell proliferation; regulation of developmental process; regulation of DNA-templated transcription
Cellular component: nucleoplasm; plasma membrane; receptor complex; cell surface; cytosol; endoplasmic reticulum membrane; extracellular region; Golgi membrane; membrane; nucleus
Genetic constraint (gnomAD): Loss-of-function variants: 87 observed, 183.81 expected, observed/expected ratio (o/e) 0.47, 90% interval 0.4 to 0.57. The upper end of that interval is the gene's LOEUF score, 0.57, which puts it in group 2 of 6, group 1 being the genes least tolerant of losing a copy. Missense variants: 2,740 observed, 3,022.2 expected, observed/expected ratio (o/e) 0.91, 90% interval 0.88 to 0.94. Synonymous variants: 1,329 observed, 1,240.9 expected, observed/expected ratio (o/e) 1.07, 90% interval 1.02 to 1.12.
Gene-disease validity (ClinGen):
ClinGen rates the evidence that NOTCH3 causes each of these diseases.
inherited thrombocytopenia (autosomal recessive): Limited. An instance of thrombocytopenia that is inherited.
pulmonary arterial hypertension (autosomal dominant): Disputed. Pulmonary arterial hypertension (PAH) is a group of diseases characterized by mean pulmonary artery pressure >20 mmHg and elevated pulmonary arterial resistance leading to right heart failure.
Homologues: Orthologues: chimpanzee NOTCH3 (99% identical), macaque NOTCH3 (99% identical), dog NOTCH3 (94% identical), pig NOTCH3 (93% identical), rat Notch3 (92% identical), mouse Notch3 (91% identical), rabbit NOTCH3 (87% identical), guinea pig NOTCH3 (80% identical), tropical clawed frog notch3 (61% identical), zebrafish notch3 (61% identical). Paralogues in human: NOTCH2 (52% identical), NOTCH1 (52% identical), SNED1 (16% identical), NOTCH2NLR (4% identical), NOTCH2NLC (4% identical), NOTCH2NLB (4% identical), NOTCH2NLA (4% identical).
Diseases named in the same sentence as NOTCH3 in open-access papers:
NOTCH3 is named in the same sentence as 388 diseases in open-access papers, as found by Europe PMC text mining. Sharing a sentence is not in itself a finding about the gene and the disease. The quoted sentences say what the papers report.
CADASIL (244 papers, 2007 to 2026). "Cerebral autosomal dominant arteriopathy with subcortical infarcts and leukoencephalopathy (CADASIL) is the most prevalent hereditary cerebral small vessel disease (cSVD), primarily caused by pathogenic variants in the NOTCH3 gene." (PMID 42006602, 2026). "Cerebral autosomal dominant arteriopathy with subcortical infarcts and leukoencephalopathy (CADASIL) is a hereditary small arteriolar disease caused by mutations in the NOTCH3 gene." (PMID 41669348, 2026). "NOTCH3 variants cause CADASIL (cerebral autosomal dominant arteriopathy and subcortical infarcts and leukoencephalopathy), the most common monogenetic form of small vessel disease (SVD) and vascular dementia (VaD)." (PMID 41931622, 2026). "This study proposes that the NOTCH3 mutation location is a central factor in the phenotypic heterogeneity of CADASIL." (PMID 40470487, 2025). "Several patients with CADASIL have been identified since the NOTCH3 mutation was discovered in 1993 with marked phenotypic variability." (PMID 40486355, 2025). "In order to examine the presence of CADASIL cases in Crete, we report a family with two affected members harboring the novel p.Cys206Trp variant in exon 4 of the NOTCH3 gene, further expanding the genotypic spectrum of pathogenic NOTCH3 variants." (PMID 40999599, 2025). "In this study we aimed to examine the presence of pathogenic NOTCH3 variants in individuals with suspected CADASIL on the Greek island of Crete." (PMID 40999599, 2025). "Cysteine-altering NOTCH3 variants linked to CADASIL have a prevalence of 3.4 individuals per 1000 in the global population, with a notably higher frequency of 9.0 individuals per 1000 in East Asia." (PMID 40869930, 2025). "Migraine with aura (MA) is a hallmark feature of CADASIL, a hereditary small-vessel disease caused by NOTCH3 mutations." (PMID 40169951, 2025). "The most common form of monogenic strokes is cerebral autosomal dominant arteriopathy with subcortical infarcts and leukoencephalopathy (CADASIL), which is caused by mutations in the NOTCH3 gene." (PMID 41356923, 2025). "NOTCH3 gene variants are associated with cerebral autosomal dominant arteriopathy with subcortical infarcts and leukoencephalopathy (CADASIL)." (PMID 40999599, 2025). "Classical CADASIL is caused by mutations in the NOTCH3 gene located on chromosome 19p13, which is involved in the differentiation and maturation of vascular smooth muscle cells, vascular development during embryogenesis, and vascular integrity." (PMID 41018180, 2025). "Cerebral autosomal dominant arteriopathy with subcortical infarcts and leukoencephalopathy (CADASIL) is a monogenic cerebral small-vessel disease caused by mutations in NOTCH3 and is the most common hereditary cerebral small-vessel disease in adults." (PMID 40470487, 2025). "CADASIL is caused by mutations in the NOTCH3 gene on chromosome 19, leading to abnormal accumulation of NOTCH3 protein in vascular smooth muscle cells." (PMID 41356923, 2025). "These clustered cysteine mutations are highly reminiscent of cysteine-altering variants in NOTCH3 that cause cerebral autosomal dominant arteriopathy with subcortical infarcts and leukoencephalopathy (CADASIL)." (PMID 40127276, 2025). "CADASIL is a small-vessel disease caused by pathogenic variants of NOTCH3, resulting in recurrent stroke, cognitive impairment, and psychiatric disturbances." (PMID 40982447, 2025). "The vascular lesions in CADASIL are caused by mutations in the NOTCH3 gene, and previous studies have confirmed the overactivation of the NOTCH pathway in CADASIL." (PMID 41000387, 2025). "Cerebral autosomal dominant arteriopathy with subcortical infarcts and leucoencephalopathy (CADASIL) is the most important heritable cause of adult vascular dementia and stroke and results from mutation of the NOTCH3 gene located on chromosome 19." (PMID 40486355, 2025).
CADASIL (continued). "Mutations in NOTCH3 cause CADASIL, a dominantly inherited condition, linked to recurrent stroke and vascular dementia and associated with accumulation of the ECD of NOTCH3." (PMID 40764588, 2025). "Certain missense mutations in NOTCH3 cause a dominantly inherited small vessel disease, CADASIL (Cerebral Autosomal Dominant Arteriopathy with Subcortical Infarcts and Leukoencephalopathy), which is associated with recurrent strokes and vascular dementia." (PMID 40764588, 2025). "This study was performed in patients with CADASIL, a genetic disorder caused by a mutation of the NOTCH3 gene with a very distinct pathophysiology and rapid lesion growth." (PMID 40832975, 2025). "Still, these findings suggest a possible need to revisit the concept of CADASIL (characterized by cerebral small-vessel disease caused by NOTCH3 mutations) as a disease." (PMID 41018180, 2025). "CADASIL is caused by pathogenic variants in NOTCH3, and the distribution of pathogenic variants varies significantly across populations." (PMID 40982447, 2025). "Disease severity in CADASIL is highly variable and is mainly determined by the position of the pathogenic NOTCH3 variant in the NOTCH3 ectodomain." (PMID 40265482, 2025). "Cerebral autosomal dominant arteriopathy, subcortical infarcts, and leukoencephalopathy (CADASIL) is the most common monogenic small vessel disease which is caused by mutation of NOTCH3 gene." (PMID 39853935, 2025). "The possibility of an adult-onset leucodystrophy was entertained, and the diagnosis of CADASIL was confirmed through genetic testing, which identified a mutation in the NOTCH3 gene." (PMID 40486355, 2025). "Background/Objectives: Cerebral autosomal dominant arteriopathy with subcortical infarcts and leukoencephalopathy (CADASIL) is a prevalent Mendelian disorder caused by mutations in the NOTCH3 gene, primarily impacting cerebral small blood vessels." (PMID 40869930, 2025). "CADASIL is caused by heterozygous cysteine-altering variants in the epidermal growth factor-like repeat (EGFr) regions of NOTCH3, which result in the mispairing of cysteine residues and altered disulphide bridge formation." (PMID 41300806, 2025). "Cerebral autosomal dominant arteriopathy with subcortical infarcts and leukoencephalopathy (CADASIL) is a monogenic form of cSVD) due to mutations in the NOTCH3 gene." (PMID 40542975, 2025). "Better characterization of NOTCH3 cysteine-sparing mutations in patients with clinical suspicion of CADASIL can offer insights into the pathomechanisms underlying CADASIL and aid in managing affected individuals." (PMID 39201482, 2024). "Following the identification of NOTCH3 as a causative gene for CADASIL, not only the pathological but also the biological role of NOTCH3 in vessels have been focused on." (PMID 38254727, 2024). "The role of genetic testing in diagnosing CADASIL is well established, with mutations in the NOTCH3 gene being responsible for the disease." (PMID 39507177, 2024). "CADASIL (cerebral autosomal dominant arteriopathy with subcortical infarcts and leukoencephalopathy) is caused by NOTCH3 mutations affecting the number of cysteines." (PMID 39201482, 2024). "We included 20 publications from 298 identified for screening and extracted data on 268 NOTCH3 cysteine-sparing mutations individuals with clinical suspicion of CADASIL." (PMID 39201482, 2024). "The hereditary nature of CADASIL is also well documented, with a significant chance of passing the NOTCH3 mutation to offspring in an autosomal dominant pattern." (PMID 39507177, 2024). "Remarkably, this phenomenon mirrors a key pathological feature found in brains of patients with CADASIL, a hereditary vascular dementia associated with NOTCH3 missense mutations." (PMID 38015629, 2024). "Cerebral autosomal dominant arteriopathy with subcortical infarcts and leukoencephalopathy (CADASIL) is one of the most common inherited cerebral small vessel diseases caused by the NOTCH3 gene mutation." (PMID 39759869, 2024).
CADASIL (continued). "Some researchers found that NOTCH3 D80G mutation carriers in four families showed typical neuroimaging and clinical phenotypes of CADASIL." (PMID 39759869, 2024). "Mutations in Notch3 have been identified as the cause of diseases such as CADASIL, infantile myofibromatosis, early-onset arteriopathy with cavitating leukodystrophy, lateral meningocele syndrome, and cancer." (PMID 38790158, 2024). "CADASIL is a genetic vasculopathy caused by the mutation of the NOTCH3 gene that leads to NOTCH3 protein accumulation in the blood vessel wall, hence the thickening of the blood vessel wall and therefore chronic small vessel hypoperfusion." (PMID 38273253, 2024). "Cerebral autosomal dominant arteriopathy with subcortical infarcts and leukoencephalopathy (CADASIL) is one kind of monogenic hereditary small-vessel disease in the brain caused by mutations in the NOTCH3 gene." (PMID 38489688, 2024). "In this review, we introduce animal and cellular models of CADASIL to discuss the pathophysiology of CADASIL-causing NOTCH3 mutations." (PMID 38254727, 2024). "Cerebral autosomal dominant arteriopathy with subcortical infarcts and leukoencephalopathy (CADASIL) is a rare genetic disorder caused by mutations in the NOTCH3 gene, resulting in subcortical infarctions and leukoencephalopathy." (PMID 38826931, 2024). "Cerebral autosomal dominant arteriopathy with subcortical infarcts and leukoencephalopathy (CADASIL) is the most common monogenic form of cerebral small vessel disease, caused by a mutation in the NOTCH3 gene on chromosome 19." (PMID 38610637, 2024). "Cerebral autosomal dominant arteriopathy with subcortical infarcts and leucoencephalopathy (CADASIL) is caused by mutations in the NOTCH3 gene." (PMID 38596173, 2024). "Cerebral autosomal dominant arteriopathy with subcortical infarcts and leukoencephalopathy (CADASIL) is an inherited cerebrovascular disease caused by the neurogenic locus notch homolog protein 3 (NOTCH3) gene mutation." (PMID 39465783, 2024). "A diagnosis of CADASIL can be made when molecular gene detection identifies the presence of the heterozygous pathogenic variation of NOTCH3." (PMID 39465783, 2024). "As the main pathogenic substance associated with CADASIL, NOTCH3 aggregation in blood vessels exists in all stages of disease progression and can even appear ten years earlier than clinical symptoms." (PMID 39759869, 2024). "CADASIL is caused by heterozygous variants in NOTCH3,1,3 primarily resulting in the gain or loss of cysteine in an EGFR of the extracellular domain." (PMID 39191170, 2024). "We first compared the DTI-ALPS index between CADASIL patients and healthy individuals and analysed its difference between symptomatic CADASIL patients and preclinical NOTCH3 cysteine-altering variant carriers." (PMID 38162905, 2024). "In conclusion, our study clearly demonstrated impaired cerebral ISF dynamics in patients with CADASIL, whereas preclinical carriers of NOTCH3 variants exhibited normal cerebral ISF dynamics comparable to that of healthy controls." (PMID 38162905, 2024). "Cerebral autosomal dominant arteriopathy with subcortical infarcts and leukoencephalopathy (CADASIL) is a condition caused by mutations in NOTCH3 and results in a phenotype characterised by recurrent strokes, vascular dementia and migraines." (PMID 37422595, 2023). "In this study, we report on the development of an active immunization therapy aimed at targeting the CADASIL‐associated NOTCH3 pathology as a novel disease‐modifying therapy for the treatment of CADASIL." (PMID 36524456, 2023). "Cerebral autosomal dominant arteriopathy with subcortical infarcts and leukoencephalopathy (CADASIL) is caused by gain-of-function mutations in the NOTCH3 gene, located on chromosome 19q13." (PMID 37628876, 2023). "Among the 750 patients identified, 150 were reviewed, of which 13% had a NOTCH3 mutation and/or clinically diagnosed CADASIL." (PMID 37521283, 2023).
CADASIL (continued). "Cerebral Autosomal Dominant Arteriopathy with Subcortical Infarcts and Leukoencephalopathy (CADASIL) is the most common genetic small vessel disease caused by variants in the NOTCH3 gene." (PMID 37361999, 2023). "Previous research has identified Notch3 as a diagnostic marker for cerebral autosomal dominant arteriopathy with subcortical infarcts and leukoencephalopathy (CADASIL), while DLL1 has shown utility in diagnosing tuberculous meningitis." (PMID 37063841, 2023). "Cerebral autosomal-dominant arteriopathy with subcortical infarcts and leukoencephalopathy (CADASIL) is caused by NOTCH3 mutations." (PMID 37158955, 2023). "Cerebral autosomal dominant arteriopathy with subcortical infarcts and leukoencephalopathy (CADASIL) results from mutations in NOTCH3 and is the most common monogenic cause of vascular dementia, stroke, and small vessel disease." (PMID 37209821, 2023). "Mutations in NOTCH3 underlie cerebral autosomal dominant arteriopathy with subcortical infarcts and leukoencephalopathy (CADASIL), the most common inherited cerebral small vessel disease." (PMID 36470429, 2023). "In this report, we develop a novel active immunization strategy in a preclinical CADASIL model and demonstrate its ability to prevent NOTCH3 ECD aggregation, which is a key hallmark of CADASIL pathophysiology." (PMID 36524456, 2023). "Cysteine‐related mutations in NOTCH3 were confirmed to be the cause of CADASIL, but recent studies have also identified the pathogenicity of cysteine‐sparing NOTCH3 mutations, such as the p.R75P mutation in Korea and Japan." (PMID 37237429, 2023). "Cerebral autosomal dominant arteriopathy with subcortical infarcts and leukoencephalopathy (CADASIL), a rare hereditary cerebral small vessel disease (cSVD) caused by NOTCH3 gene mutations, is a major cause of stroke and dementia in middle-aged adults." (PMID 37542975, 2023). "Here, we report pathogenic, likely pathogenic, and benign changes in the selected exons of the NOTCH3 gene in patients with CADASIL and suspected or diagnosed CADASIL syndrome." (PMID 37873835, 2023). "CADASIL is a rare hereditary small vessel disease (SVD) caused by mutations in the NOTCH3 (Notch Homolog 3) gene situated on chromosome 19." (PMID 37628924, 2023). "Genetic testing detected a heterozygous pathogenic variant NM_000435.3:c.1364G > T p.(Cys455Phe) in NOTCH3, which is associated with cerebral autosomal dominant arteriopathy with subcortical infarcts and leukoencephalopathy (CADASIL)." (PMID 37476306, 2023). "Patients with CADASIL have a gain-of-function mutation in NOTCH3 that results in the deposition of microscopic aggregates around the smooth muscle cells with the characteristic appearance of granular osmiophilic material (GOM) on electron microscopic studies." (PMID 36984587, 2023). "The most common inherited cause of vascular dementia and stroke, cerebral autosomal dominant arteriopathy with subcortical infarcts and leukoencephalopathy (CADASIL), is caused by mutations in NOTCH3." (PMID 36753487, 2023). "This study aimed to observe the presence or absence of a correlation between selected genetic variants of the NOTCH3 gene and the clinical characteristics of patients with CADASIL." (PMID 37873835, 2023). "The most well-known is cerebral autosomal-dominant arteriopathy with subcortical infarcts and leukoencephalopathy (CADASIL), sustained by mutations in NOTCH3." (PMID 37048668, 2023). "CADASIL is caused by mutations in the NOTCH3 gene, coding for the Notch 3 receptor, which results in impaired function of vascular smooth muscle cells." (PMID 38002991, 2023). "Over 280 distinct NOTCH3 mutations cause CADASIL and result in the extracellular domain of NOTCH3 accumulating in the walls of arterioles, with the diagnostic pathological feature of GOM in blood vessel walls seen on electron microscopy." (PMID 36564356, 2023).